MEN1 (menin 1)
Diseases named in the same sentence as MEN1 in open-access papers (continued):
Sharing a sentence is not in itself a finding about the gene and the disease.
papillary thyroid carcinoma (4 papers, 2012 to 2023). "We experienced a sporadic case of MEN1 complicated with papillary thyroid carcinoma (PTC) and found a novel missense mutation in the patient's MEN1 gene." (PMID 37179722, 2023). "No other mutations were observed in exons 8 and 9 of the gsα gene, therefore, the G7848A mutation within exon 10 of the MEN1 gene may represent the molecular pathology underlying pituitary somatotroph adenomas and papillary thyroid carcinoma." (PMID 25663877, 2015). "Only three cases of papillary thyroid cancer combined with MEN1 were reported in the literature and seems that these cases did not correlate to MEN1." (PMID 23091757, 2012).
pituitary carcinoma (4 papers, 2017 to 2019). A primary or metastatic malignant neoplasm affecting the pituitary gland. "Pituitary carcinomas rarely occur in genetic syndromes; examples of pituitary carcinoma patients with MEN1 mutations have been documented, whilst AIP, PRKAR1A, DICER1 and GPR101 mutations have not been associated with metastatic spread to date." (PMID 28284009, 2017).
sarcoma (4 papers, 2012 to 2021). A usually aggressive malignant neoplasm of the soft tissue or bone.
thymic neuroendocrine tumor (4 papers, 2020 to 2026). Thymic endocrine tumor is a rare, malignant, primary thymic neoplasm originating from neuroendocrine cells, presenting as a mass within the anterior mediastinum. "Herein, we observed a family carrying the MEN1 p.L105Sfs*14 mutation in which two males were diagnosed with MEN1-associated thymic neuroendocrine tumors (NETs)." (PMID 41736142, 2026). "Approximately 25% of patients with thymic carcinoid tumors harbor a MEN1 germline mutation and 8% of MEN1 patients develop thymic neuroendocrine tumors." (PMID 33641055, 2021). "This case report observed a family that presented with MEN1 p.L105Vfs mutation, and two of the family members had been diagnosed with thymic neuroendocrine tumor combined with MEN1." (PMID 32126984, 2020). "A frameshift mutation (p.L105Vfs) of MEN1 was detected in the thymic neuroendocrine tumor of the proband." (PMID 32126984, 2020). "For instance, diffuse loss of nuclear menin (protein encoded by MEN1) immunostaining in multifocal pulmonary neuroendocrine (micro)tumors or thymic neuroendocrine tumors should alert diagnosticians to the possibility of MEN1 syndrome even in the absence of a family history." (PMID 33641055, 2021). "Ectopic tumoral ACTH secretion has also been observed in MEN1, almost exclusively originating from thymic neuroendocrine tumors." (PMID 37409236, 2023). "Additionally, thymic neuroendocrine tumors in MEN1 are also rarely reported." (PMID 32126984, 2020). "Similarly, no MEN1 patients were among 12 cases with ectopic CS and thymic neuroendocrine tumors (NETs) who underwent surgical resection in another large retrospective study from a single institution." (PMID 37409236, 2023). "Although not well studied in the context of MEN1, such high Ki-67 indices and the increase in Ki-67 index noted on sequential operations likely represent the dominance over time of the more aggressive MEN1-null thymic neuroendocrine tumor clones." (PMID 37409236, 2023). "The reason for the obvious difference in age and prognosis between the proband and IV-1 might be that LOH of MEN1 gene was detected in the skin metastatic lesion of IV-1, but not in the thymic neuroendocrine tumor of the proband." (PMID 32126984, 2020).
thymoma (4 papers, 2021 to 2025). A neoplasm arising from the epithelial cells of the thymus. "Somatic LOH at the MEN1 locus was identified in 10 tumors including the 2 thymomas (7 through direct Sanger sequencing and an additional 3 using polymorphic markers)." (PMID 34515662, 2021). "All 4 patients with thymic NETs had underlying truncating germline MEN1 variant while the patient with thymoma had a nontruncating variant." (PMID 39946193, 2025). "Despite its rare occurrence, our case provides us with a new awareness that thymoma may coexist with MEN1." (PMID 35821790, 2022). "In the case presented here, we report a 39-year-old woman with Type AB thymoma in MEN1." (PMID 35821790, 2022).
tumor predisposition syndrome (4 papers, 2012 to 2025). "While it is now more than a decade since the first description of the gene mutation underlying the tumour predisposition syndrome multiple endocrine neoplasia type 1 (MEN1), the mechanism by which its protein product menin acts to prevent development of tumours is still poorly understood." (PMID 22708734, 2012).
bronchial NETs (3 papers, 2018 to 2023). "Only a relative small percentage of bronchial NET are associated with MEN1 (< 5%)." (PMID 30254610, 2018). "In conclusion, pancreaticoduodenectomy is essential for ZES treatment, and bronchial NET is one of the important prognostic factors for patients with MEN1." (PMID 37867522, 2023). "The prevalence of bronchial NETs in patients with MEN1 is low (2%–8%), and multiplicity is relatively common." (PMID 37867522, 2023). "The prevalence of bronchial NETs among patients with MEN1 is 4.7–31.3%." (PMID 37867522, 2023).
gastric cancer (3 papers, 2019 to 2023). A primary or metastatic malignant neoplasm involving the stomach. "KTM2A was found to have interactions with MEN1, MLL1 complex, ATR, KAT8, SP11, and PAX7 none of which have been implicated in gastric cancer before." (PMID 37287033, 2023).
gastric carcinoid tumors (3 papers, 2016 to 2025). "Risk analysis demonstrated that gastric carcinoid tumors were more frequent in MEN1/ZES patients with higher FSG levels, longer disease duration, and strong alpha-HCG staining on the biopsy." (PMID 31623145, 2019). "MEN1/ZES patients have a much higher rate of developing gastric carcinoid tumors than patients with sporadic ZES [i.e., 23–70% vs. <1%." (PMID 41463062, 2025). "From a review of the data in these studies, it was calculated that gastric carcinoid tumors are at least 70-fold more frequent in MEN1/ZES patients that in sporadic ZES." (PMID 31623145, 2019). "A very recent paper has also demonstrated reduced p27 expression in gastric carcinoid tumors arising in transgenic mice that was hypergastrinemic as a result of deletion of Men1 and somatostatin along with treatment with omeprazole." (PMID 27323780, 2016). "This estimate was calculated from the differences in the NIH prospective study of 57 consecutive MEN1/ZES patients in which gastric carcinoid tumors were found in 23% of the patients, whereas in a similar study involving 106 patients with sporadic ZES, 0% had gastric carcinoids." (PMID 41463062, 2025).
hereditary cancer (3 papers, 2016 to 2023). Malignant neoplasms occurring in families at a rate greater than that expected by chance and caused by germline mutations in a specific gene.
Hypercalciuria (3 papers, 2019 to 2024). "The consumption of fruit and vegetables is therefore essential for MEN1 patients suffering from hypercalciuria, and it is useful to provide a sufficient amount of alkalis and citrates." (PMID 38892509, 2024). "They differ from FHH based on the clinical pattern of urinary hypocalciuria (as opposed to normal or hypercalciuria in MEN1) and the risk of endocrine malignancy with MEN1 mutations." (PMID 35299844, 2021). "Though data is limited in patients with MEN1, cinacalcet has been shown to have calcium lowering effects, but current evidence does not show an improvement in bone mineral density in the spine or femur or in hypercalciuria." (PMID 31263451, 2019). "Therefore, MEN1 patients, especially those with PHPT-derived hypercalciuria, should ideally limit their dietary sodium intake to less than 1.5 mg per day." (PMID 38892509, 2024).
Hyperglycemia (3 papers, 2010 to 2021). An increased concentration of glucose in the blood. "To determine the underlying mechanisms whereby Men1 ablation prevents STZ-induced hyperglycemia, we determined cell composition in islets, BrdU incorporation by beta cells, islet size, and circulating insulin levels in control and Men1-excised mice 4 weeks after STZ injections." (PMID 21318185, 2010). "Men1 gene deletion also reverses pre‐existing hyperglycemia in high fat diet (HFD)‐induced diabetic mice as well as in obese (db/db) mice and ameliorates gestational diabetes in pregnant mice." (PMID 33821572, 2021). "We found that Men1 excision prevented STZ-induced hyperglycemia, at least partly through promoting beta-cell proliferation, and preserving the number of functional beta cells and circulating insulin levels." (PMID 21318185, 2010). "Men1 excision prevented mice from streptozotocin-induced hyperglycemia mainly through increasing the number of functional beta cells." (PMID 21318185, 2010). "Taken together, these findings strongly suggest that Men1 ablation prevents STZ-induced hyperglycemia at least in part through promoting beta-cell proliferation, resulting in the maintenance of a larger number of functional beta cells and higher circulating insulin concentrations." (PMID 21318185, 2010). "Therefore, Men1 ablation likely prevents STZ-induced hyperglycemia mainly through its impact on beta-cell proliferation and increasing the number of functional beta cells." (PMID 21318185, 2010). "Therefore, to determine whether Men1 ablation prevents STZ-induced hyperglycemia through reducing the number of alpha cells, the average number and percentage of alpha cells in islets and circulating glucagon levels were determined." (PMID 21318185, 2010). "Similar to what was observed in the TAM-treated Men1l/l; Cre-ER mice, specific Men1 excision in beta cells in the Men1l/l; RIP-Cre mice also rendered mice resistant to STZ-induced beta cell damage and hyperglycemia." (PMID 21318185, 2010). "In order to determine whether Men1 ablation prevents STZ-induced hyperglycemia partly through its regulation on Pdx-1 and/or GLUT2, we sought to detect expression or localization of Pdx-1 and GLUT2 in beta cells in STZ-treated control and Men1-excised mice by immunostaining." (PMID 21318185, 2010). "Men1-excised mice, on the other hand, did not develop hyperglycemia during the whole period of study, demonstrating that Men1 ablation prevents STZ-induced hyperglycemia." (PMID 21318185, 2010).
Li-Fraumeni syndrome (3 papers, 2012 to 2018). "Most ACCs occur sporadically, but some cases are associated with various genetic diseases, e.g., Li-Fraumeni syndrome (LFS), Beckwith–Wiedemann, and multiple endocrine neoplasia type I (MEN1)." (PMID 30158955, 2018). "A defining feature of both MEN1 and Li Fraumeni syndromes is the occurrence of multiple tumours, and a possible explanation for the decreased lifespan of the dual heterozygous animals compared to either of the individual lines may be increased overall tumour burden." (PMID 22708734, 2012).
liver cancer (3 papers, 2022 to 2025). An epithelial or non-epithelial malignant neoplasm that arises from the liver. "We report the first case of MEN1 with simultaneous liver and lung involvement in which the patient underwent radical resection of the tumors, and we propose the possibility that primary tumors of the liver can also occur in MEN1; although, this view needs further verification." (PMID 35538538, 2022).
multiple myeloma (3 papers, 2020 to 2025). "Most multiple myeloma cell lines that did not harbor MLLr were also sensitive to the genetic depletion of MEN1." (PMID 38003662, 2023).
small intestinal NETs (3 papers, 2016 to 2024). "In GEP-NETs, high serum CgA levels correlated with shorter survival and liver metastasis as reported in small intestinal NETs accompanied by up to 200 times above normal levels and up to 150 times higher MEN1 cases." (PMID 33485291, 2021).
smooth muscle tumor (3 papers, 2019 to 2025). A benign or malignant myomatous neoplasm arising from smooth muscle. "In summary, patients with MEN1 are at risk for the development of benign and occasionally malignant smooth muscle tumors." (PMID 36325452, 2022).
Beckwith-Wiedemann syndrome (2 papers, 2018 to 2023). Beckwith-Wiedemann syndrome (BWS) is a genetic disorder characterized by overgrowth, tumor predisposition and congenital malformations. "Other hereditary syndromes also underlying pancreas malignancy and hormonally active tumors include von Hipple-Lindau disease, McCune-Albright, Li-Fraumeni, MEN1, and Beckwith-Wiedemann syndrome." (PMID 37296718, 2023).
benign parathyroid neoplasms (2 papers, 2020 to 2025). "Although MEN1 mutations are a major driver in benign parathyroid neoplasms, dysfunctional MEN1 has also occasionally been reported in PC." (PMID 40762649, 2025). "The serum Ca and PTH levels in patients with MEN1-PC/APN are usually greater than in those with MEN1-associated benign parathyroid tumors." (PMID 33101196, 2020).
Birt-Hogg-Dube syndrome (2 papers, 2022). "In addition to MEN1, the genodermatoses associated with collagenomas include familial cutaneous collagenoma, Birt-Hogg-Dubé Syndrome, Buschke-Ollendorff syndrome, proteus syndrome, and TSC, in which the collagenoma is known as a shagreen patch." (PMID 36325452, 2022). "Therefore, even though trichodiscomas and acrochordons are typical findings in Birt-Hogg-Dubé syndrome, differential diagnoses with alternative causes, such as MEN1, might be useful to take into consideration in some cases in order to provide proper diagnosis and management." (PMID 36428828, 2022). "However, trichodiscomas and acrochordons have been reported in patients with MEN1, without Birt-Hogg-Dubé syndrome." (PMID 36428828, 2022).
cutaneous melanoma (2 papers, 2022 to 2024). A primary melanoma arising from atypical melanocytes in the skin. "This study highlights MEN1 as a potent tumor-suppressor pathway that efficiently blocks tumorigenesis in cutaneous melanoma." (PMID 38891107, 2024). "In this study, we identified the TGFβ/Smad3/MEN1 signaling axis as a potent tumor-suppressor pathway in cutaneous melanoma." (PMID 38891107, 2024). "Overall, this study defines the TGFβ/MEN1 axis as a potent tumor-suppressor pathway in cutaneous melanoma and provides novel perspectives for tailor-made targeted therapies for this highly lethal malignancy." (PMID 38891107, 2024). "However, in whole exome sequencing of 331 cutaneous melanoma patients studied in The Cancer Genome Atlas program, MEN1 variants were not reported." (PMID 36325452, 2022).
diffuse large B-cell lymphoma (2 papers, 2023 to 2024). "Polycomb repressive complex 2 (PRC2)-mediated H3K27 tri-methylation regulates the genome-wide distribution of MLL1 and MEN1 in diffuse large B-cell lymphoma (DLBCL) cells." (PMID 38279330, 2024).
duodenal neuroendocrine tumors (2 papers, 2022 to 2023). "Pancreatic or duodenal neuroendocrine tumors are discovered when a related endocrine syndrome occurs, or during abdominal examination performed for surveillance of MEN1 patients and asymptomatic carriers of MEN1 gene mutation." (PMID 37894286, 2023).
duodenal tumors (2 papers, 2017 to 2021). "The patient in this case was first suspected of having MEN1 based on the clinical findings of multiple peptic lesions accompanied by high levels of serum gastrin, calcium, and intact PTH, pancreatic and duodenal tumors suspected for NETs, and a urinary tract stone." (PMID 28270118, 2017).
Ewing sarcoma (2 papers, 2017 to 2023). A small round cell tumor that lacks morphologic, immunohistochemical, and electron microscopic evidence of neuroectodermal differentiation. "We again interrogated publically available CCLE gene expression data, and found menin (MEN1) expression to be robust in Ewing sarcoma." (PMID 27888797, 2017).
exocrine insufficiency of the pancreas (2 papers, 2022 to 2023). "The quality of life of MEN1 patients who are submitted to major pancreatic resections can be negatively affected by endocrine and/or exocrine insufficiency of the pancreas." (PMID 37894286, 2023).
gastric adenocarcinoma (2 papers, 2023 to 2024). "We evaluated the subcellular localization and half-lives of the mutants and variant in Men1-null mouse embryo fibroblast cells and in hormone-expressing human gastric adenocarcinoma and NET cell lines." (PMID 37492626, 2023). "LOH at the MEN1 locus is reported to occur in less than 50% of duodenal gastrinomas, thus, we performed the subsequent structure–function studies in gastric adenocarcinoma and NET cell lines expressing varying levels of endogenous menin." (PMID 37492626, 2023).
hyperparathyroidism jaw-tumour syndrome (2 papers, 2019 to 2022). "All patients were clinically assessed for a history compatible with hyperparathyroidism jaw-tumour syndrome or MEN1, eventually including genetic screening." (PMID 36612195, 2022). "PC is usually sporadic, but may be part of familial syndromes such as hyperparathyroidism-jaw tumour syndrome (HPT-JT), isolated familial hyperparathyroidism (FIHP) and, rarely, MEN1 or MEN2A." (PMID 31176307, 2019).
Impaired glucose tolerance (2 papers, 2020 to 2025). An abnormal resistance to glucose, i.e., a reduction in the ability to maintain glucose levels in the blood stream within normal limits following oral or intravenous administration of glucose. "Interestingly, a few reports have indicated that MEN1 patients are prone to impaired glucose tolerance." (PMID 32884006, 2020).
intellectual disabilities (2 papers, 2021 to 2024).
intracranial hypertension (2 papers, 2019 to 2023). A finding characterized by increased cerebrospinal fluid pressure within the skull. "None of them was larger than 60 mm or presented hydrocephalus or intracranial hypertension (ICH) as initial manifestation of MEN1." (PMID 31555208, 2019).
liposarcoma (2 papers, 2023). A usually painless malignant tumor that arises from adipose tissue. "One individual had well-differentiated liposarcoma, which has been previously reported in a single case of MEN1." (PMID 36967793, 2023).